ATOH1 (atonal bHLH transcription factor 1)
Description:
Transcriptional regulator. Activates E box-dependent transcription in collaboration with TCF3/E47, but the activity is completely antagonized by the negative regulator of neurogenesis HES1. Plays a role in the differentiation of subsets of neural cells by activating E box-dependent transcription (By similarity).
Synonyms: bHLHa14; hATH1; ATH1; MATH-1; Math1; DFNA89
Tractability: No criterion of Open Targets' tractability assessment is met for any kind of drug.
Gene: Protein-coding gene on chromosome 4 (93,828,753 to 93,830,964, forward strand). Ensembl gene ENSG00000172238.
Subcellular location: Nucleus
Subcellular location (Human Protein Atlas): Nucleoplasm; Cytosol
Gene Ontology:
Molecular function: sequence-specific double-stranded DNA binding; DNA-binding transcription factor activity; DNA-binding transcription factor activity, RNA polymerase II-specific; E-box binding; chromatin DNA binding; DNA binding; DNA-binding transcription activator activity, RNA polymerase II-specific; protein dimerization activity; RNA polymerase II cis-regulatory region sequence-specific DNA binding; sequence-specific DNA binding
Biological process: axon development; central nervous system development; neuron fate commitment; positive regulation of neuron differentiation; positive regulation of transcription by RNA polymerase II; sensory organ development; transcription by RNA polymerase II; negative regulation of gliogenesis; positive regulation of inner ear receptor cell differentiation; system development
Cellular component: chromatin; nucleus
Genetic constraint (gnomAD): Loss-of-function variants: 9 observed, 20.48 expected, observed/expected ratio (o/e) 0.44, 90% interval 0.26 to 0.77. The upper end of that interval is the gene's LOEUF score, 0.77, which puts it in group 3 of 6, group 1 being the genes least tolerant of losing a copy. Missense variants: 516 observed, 500.53 expected, observed/expected ratio (o/e) 1.03, 90% interval 0.96 to 1.11. Synonymous variants: 247 observed, 230.21 expected, observed/expected ratio (o/e) 1.07, 90% interval 0.97 to 1.19.
Homologues: Orthologues: chimpanzee ATOH1 (99% identical), macaque ATOH1 (98% identical), dog ATOH1 (92% identical), pig ATOH1 (91% identical), rabbit ATOH1 (88% identical), rat Atoh1 (88% identical), mouse Atoh1 (88% identical), zebrafish atoh1a (44% identical), tropical clawed frog atoh1 (42% identical), Drosophila melanogaster ato (17% identical), Drosophila melanogaster amos (15% identical), Caenorhabditis elegans lin-32 (14% identical), and 2 more. Paralogues in human: NEUROD2 (20% identical), NEUROD1 (18% identical), NEUROD6 (18% identical), NEUROD4 (18% identical), ATOH7 (15% identical), BHLHE22 (15% identical), NEUROG2 (15% identical), OLIG2 (15% identical), NEUROG1 (14% identical), NEUROG3 (14% identical), BHLHE23 (13% identical), OLIG1 (12% identical), and 3 more.
Diseases named in the same sentence as ATOH1 in open-access papers:
ATOH1 is named in the same sentence as 77 diseases in open-access papers, as found by Europe PMC text mining. Sharing a sentence is not in itself a finding about the gene and the disease. The quoted sentences say what the papers report.
medulloblastoma (51 papers, 2010 to 2025). A malignant, invasive embryonal neoplasm arising from the cerebellum. "Conversely, overexpression of ATOH1 in a PTCH1-deficient mouse model of SHH-activated medulloblastoma accelerates tumor progression." (PMID 34012965, 2021). "Atoh1 activity works to drive medulloblastoma only in the context of underlying Shh mutations, whereas Atoh1 loss of function prevents medulloblastoma formation due to decreased granule neuron precursor proliferation and impaired Shh signalling." (PMID 29759978, 2018). "Indeed, dysregulation of the Atoh1-mediated gene regulatory network can cause cerebellar neoplasia leading to medulloblastoma." (PMID 39833721, 2025). "Interestingly, ATOH1 is also implicated in promoting medulloblastoma formation." (PMID 28134287, 2017). "Although the significance of the possible association between Atoh1 expression and glucose metabolism is presently unclear, we note that Atoh1 can function as an oncogene in medulloblastomas or a tumor suppressor gene in adenomatous polyposis carcinoma." (PMID 39833721, 2025). "ATOH1 impact in cancer is context dependent, described as a tumor suppressor in colorectal cancer and an oncogene in medulloblastoma." (PMID 40305287, 2025). "Both types of GNPs express ATOH1, suggesting that ATOH1 is a marker of the SHH medulloblastoma progenitor [3, 6••, 7]." (PMID 37943476, 2023). "Another point to raise in this context is that Atoh1, Gli3, and Mycn are all up-regulated in a subtype of medulloblastoma that originates from GCs." (PMID 37491148, 2023). "The deletion of Atoh1 is able to prevent the formation of medulloblastoma, highlighting the important role it plays in regulating cell proliferation." (PMID 36895790, 2023). "Other BHLH family members are reported in cancer biology and clinical outcomes, especially brain cancers like ASCL1 in glioma and neuroblastoma, Olig2 in astrocytoma, and ATOH1 in medulloblastoma." (PMID 35806162, 2022). "The most robust of these relationships is demonstrated by ATOH1-mediated transcriptional control of development and medulloblastoma progression." (PMID 34012965, 2021). "Recently, a phosphorylated form of ATOH1 was found in human SHH-activated medulloblastoma samples and serves to stabilize ATOH1, leading to increased ATOH1-mediated activity and proliferation of tumor initiating cells." (PMID 34012965, 2021). "The requirement of ATOH1 for the formation of SHH-activated medulloblastoma is mediated by direct binding of ATOH1 to the SHH pathway effector, GLI2, which maintains GCPs in a SHH-responsive state." (PMID 34012965, 2021). "The increased expression profile of ATOH1 in medulloblastoma – a cerebellar tumor subtype – is thought to reflect the prominent role of ATOH1 as a regulator of cerebellar GPCs in the developing brain." (PMID 34012965, 2021). "For example, a rare population of CD15-positive cells identified in human medulloblastomas and from a Ptch1+/− medulloblastoma mouse model also express ATOH1 (also known as MATH1), and so resemble granule neuron precursors rather than stem cells." (PMID 29759978, 2018). "Inhibiting Jak2 reduced the levels of Atoh1 in medulloblastoma cells and slowed tumor growth in mice." (PMID 29168692, 2017). "We have shown that the transcription factor Atonal homologue 1 (Atoh1) is required for Shh-type medulloblastoma development in mice." (PMID 29168692, 2017). "NESTIN and ATOH1 were expressed in some medulloblastoma cell lines but also in other tumor cell lines." (PMID 27310018, 2016). "The combined activation of GLI1 and atonal homolog 1 (ATOH1) (transcription factor) in primary GNP resulted in increased medulloblastoma formation." (PMID 26633513, 2015). "These medulloblastomas arise from granule neuron progenitors (GNP) and express the Atoh1 transcription factor, which is essential for development of medulloblastomas in mice as its inactivation suppresses medulloblastoma development." (PMID 25901736, 2015).
medulloblastoma (continued). "Atoh1 is also essential for medulloblastoma progression and Atoh1 removal reduces the progression of this childhood tumor." (PMID 25698932, 2015). "As observed with cerebellar GCPs, treatment of medulloblastoma cells with WNT3 decreased the expression of ATOH1." (PMID 24303070, 2013). "Finally, recent studies have revealed that the bHLH TF Atoh1 synergizes with Gli2 to activate a medulloblastoma transcriptional network." (PMID 33006313, 2020). "Thus, medulloblastoma cells assumed a range of fates that was broader than the expected neuronal fate of the Atoh1-expressing progenitors but remained within the neuroectodermal lineage." (PMID 31863004, 2019). "In common with the regulation of other bHLH proneural genes, additional phosphorylation events potentially mediated by CDKs may play a more widespread role in controlling Atoh1 activity in both normal granule neuron precursors and in medulloblastoma." (PMID 29759978, 2018). "Atoh1/Math1 is a bHLH transcription factor required for SHH medulloblastoma development." (PMID 28333115, 2017). "To determine whether reducing either Atoh1 levels or activity in tumors after their development is beneficial, we studied Atoh1 dosage and modifications in Shh-type medulloblastoma." (PMID 29168692, 2017). "Phosphorylated Atoh1 was also detected in samples taken from human medulloblastoma tumors." (PMID 29168692, 2017). "Elevated expression of Atoh1, the basic helix-loop-helix transcription factor that is crucial for the development of the cerebellar granule neurons, can also drive uncontrolled cell proliferation and formation of medulloblastoma." (PMID 29168692, 2017). "ATOH1 promoted medulloblastoma formation together with the Shh hedgehog signaling pathway." (PMID 25950549, 2015). "It is important to understand the expression and regulation of Atoh1, not just for the generation of hair cells in the inner ear, but also for the possible contribution of this gene to diseases such as medulloblastoma in which the Atoh1 gene is thought to be improperly activated." (PMID 24265785, 2013). "Atoh1Cre/+ mice have been widely used to target well established Atoh1-lineage cells including several neurons in the hindbrain and the spinal cord, hair cells in the inner ear, secretory cells in the intestine, Merkel cells in the epidermis, and tumor cells in the medulloblastoma." (PMID 37923392, 2023). "The Atoh1Cre/+ mice have been broadly used to study the Atoh1-lineage cells in many different contexts including neurons in the hindbrain and the spinal cord, hair cells in the inner ear, secretory cells in the intestine, Merkel cells in the epidermis, and tumor cells in the medulloblastoma." (PMID 37923392, 2023). "Whilst previous analysis of genetic/epigenetic changes would not have readily identified the genes identified here, some could have been identified solely through subtype-specific overexpression (as was the case for IGF2BP1 and WNT16 in ALL and ATOH1 in medulloblastoma)." (PMID 34230614, 2021). "Thus, proliferating Atoh1-positive granule neuron precursors in medulloblastoma may be locked in a pro-tumourigenic state resulting from a failure to properly differentiate due to sustained levels of Atoh1." (PMID 29759978, 2018). "Later, by using the RCAS-TVA system, we showed that specific Atoh1-negative/glial fibrillary acidic protein (GFAP)-positive brain stem cells could generate MYCN-driven medulloblastoma by using a mutationally stabilized MYCNT58A viral construct." (PMID 28333115, 2017). "While mechanistically understudied, in medulloblastoma and MCC, ATOH1 is tumor promoting, whereas it is a tumor suppressor in CRC." (PMID 40305287, 2025). "Recent work shows that the Atoh1 transcription factor essential for GNP specification, CGN lineage survival, and medulloblastoma tumorigenesis, plays a critical role in ciliogenesis." (PMID 36895790, 2023).
medulloblastoma (continued). "The role of ATOH1 in high-grade glioma has yet to be well-defined, although correlative relationships between high ATOH1 expression in the SHH-activated subtype of medulloblastoma have been reported." (PMID 34012965, 2021). "During the processes of tumorigenesis, ATOH1 is required to attain GCP identity, which serves as a critical event for the formation of SHH-induced medulloblastomas." (PMID 34012965, 2021). "In support of WTC10 MYCN tumors representing SHH medulloblastoma, WTC10 MYCN tumors, compared to parental NES cells, showed increased expression of ATOH1, a marker of GNP cells, a cell of origin for SHH medulloblastoma." (PMID 31204176, 2019). "Atonal bHLH transcription factor 1 (ATOH1) directly regulates transcription of GLI2 in granule neuron precursors, the cell of origin of medulloblastoma, where it plays a critical role in tumorigenesis." (PMID 30158435, 2018). "ATOH1 is expressed in granule neuron precursors of the postnatal cerebellum and is highly expressed in SHH-type medulloblastomas." (PMID 29759978, 2018). "We discovered tyrosine 78 of Atoh1 is phosphorylated by a Jak2-mediated pathway only in tumor-initiating cells and in human SHH-type medulloblastoma." (PMID 29168692, 2017). "In addition to attempting to inhibit SHH signaling—a strategy that can be foiled by the development of secondary mutations —we hypothesized that controlling the levels of Atoh1 protein will provide another therapeutic entry point for the treatment SHH-driven medulloblastoma." (PMID 29168692, 2017). "These lack Atoh1 expression and MMP9 is reduced in comparison to Ptch1Δ/+ medulloblastomas, while the expression of some differentiation markers is increased." (PMID 25901736, 2015). "In particular the transcription factor Atoh1, whose expression is essential for development of SHH subgroup medulloblastomas is lost." (PMID 25901736, 2015). "The NeuroD2:SmoA1 medulloblastoma model was also used to show that blocking TGF-β signaling promoted memory T cell development thereby conferring antitumor immunity and in Atoh1-Cre;Ptch1fl/fl mice, tumor astrocyte-derived Shh induced the proliferation of medulloblastoma tumor cells." (PMID 33869004, 2021). "While ATOH1 expression alone is not sufficient to induce medulloblastoma tumorigenesis, deletion of ATOH1 in a mouse model of medulloblastoma significantly attenuates tumorigenesis by decreasing GPC proliferation." (PMID 34012965, 2021). "However, ATOH1 activation alone was not enough to induce medulloblastomas." (PMID 26633513, 2015). "However, this study does draw parallels with the ATOH1 pro-invasive phenotype in MCC76 and its pro-metastatic role in medulloblastoma, where the ability of ATOH1 to suppress cell death was not explored." (PMID 40305287, 2025). "In addition, ATOH1, GLI2, and SOX1 protein levels were significantly reduced in SI-CSC medulloblastomas but not in SD-CSC medulloblastomas that were resistant to LDE225." (PMID 36688010, 2022). "Although our study showed the NES cells can generate SHH medulloblastoma, these cells were not primed to generate GNP cells, as the transcriptomes were quite distinct and spontaneous differentiation of NES cells does not lead to maximal expression of the GNP marker ATOH1." (PMID 31204176, 2019).
colorectal cancer (14 papers, 2009 to 2025). A primary or metastatic malignant neoplasm that affects the colon or rectum. "We expressed forms of ATOH1 where S/T-P sites were mutated to alanine-proline (AP) in colorectal cancer cells to determine the effect of ATOH1 phosphorylation on cell proliferation and on expression of markers of differentiation." (PMID 30100168, 2018). "Consistent with this, a phosphomutant form of ATOH1 enhances the expression of gene sets associated with a more mature secretory phenotype in colorectal carcinoma cells." (PMID 30100168, 2018). "Furthermore, colorectal cancer and Merkel cell carcinoma patients show genetic and epigenetic ATOH1 loss-of-function mutations." (PMID 19243219, 2009). "Notch plays an important role in the self-renewal of colorectal cancer stem cells and it prevents apoptosis by inhibiting transcription factors such as cell cycle regulatory proteins P27 and ATOH1." (PMID 31198409, 2019). "Atoh1 was significantly elevated in colorectal cancer (CRC) cells stimulated by exogenous SCF or overexpressing c-KIT in vitro, while decreased by the blockage of SCF/c-KIT signaling with Imatinib." (PMID 29786668, 2018). "In colorectal cancer cells, ATOH1 overexpression reduced proliferation and growth in soft agar and xenografts, and deletion of ATOH1 enhanced tumorigenicity in mice." (PMID 25950549, 2015). "Previous studies showed that 70% of colorectal cancer patient samples have significantly decreased expression of ATOH1 compared to tissue-matched normal LI samples, and revealed ATOH1 as a tumor suppressor in vitro and in vivo." (PMID 25751518, 2015). "Interestingly, the Atonal bHLH transcription factor 1 (ATOH1), which was associated with good survival in our analyses of patients with stage II colorectal cancer, has been also associated with good survival in colorectal cancer, independent of stage." (PMID 37654625, 2023). "In mammals, two aggressive human cancers derive from tissues where ATOH1 instructs cell fate commitment, namely Merkel cell carcinoma (MCC) and colorectal cancer (CRC)." (PMID 19243219, 2009).
colon cancer (11 papers, 2009 to 2023). "Gain- and loss-of-function analyses point to Atoh1-dependent regulation of proliferation in mouse colon tumors." (PMID 19243219, 2009). "In summary, gain- and loss-of-function studies in mouse colon cancer models and human cancer cells support a conserved antitumor function for ATOH1 mediated by JNK and p21." (PMID 19243219, 2009). "We asked whether ATOH1 could be a pivotal factor in causing colon cancer in mice and humans." (PMID 19243219, 2009). "While our studies show that loss of TNF function expands the number of ATOH1+ cells, another group has shown that TNF can stabilize ATOH1 in the context of colon cancer." (PMID 37643009, 2023). "Colon cancer cells were enriched in stemness through atonal homolog 1(ATOH1) protein by stabilization of TNF‐α." (PMID 36550571, 2022). "In this work, we retrospectively identified four bone metastasis-related genes (INHBB, RBP7, RTN2, and ATOH1) and constructed a gene expression signature model for colon cancer patients by bioinformatic analysis." (PMID 34421995, 2021). "In colon cancer tissues, positive expression of ATOH1 is closely related to a lower grade, a lower TNM stage, and better overall survival." (PMID 34421995, 2021). "We have taken advantage of the intact Notch signaling in the colon cancer cell line LS-174T and designed cell-based transcription assays to measure Notch target Atoh1 gene expression." (PMID 30540745, 2018). "By examining gene expression in a panel of colon cancer cell lines, we found that LS-174T cells express Atoh1 and that this expression can be modulated by Notch signaling, making it suitable for studying Notch signaling-dependent Atoh1 transcription." (PMID 30540745, 2018). "Here we report using a colon cancer cell line LS-174T, which displays Notch inhibition-dependent Atoh1 expression as a surrogate cellular model to screen for inducers of Atoh1 expression." (PMID 30540745, 2018). "Recent studies in colon cancer cell lines suggest that ATOH1 can inhibit tumor cell growth in vitro." (PMID 19243219, 2009). "However, there was a contradictory finding which stated that miR-613 deteriorated colon cancer by targeting ATOH1 and motivating JNK1 signaling." (PMID 33495420, 2021). "Treatment of colon tumors with anti-DLL4 up-regulates markers of more differentiated colon cells (for example, ATOH1 and Chromogranin A) indicating that DLL4-Notch inhibition limits the stem/progenitor-like properties of colon tumor cells and promotes a more differentiated phenotype." (PMID 21831306, 2011).